CD4 (CD4 molecule)
Diseases named in the same sentence as CD4 in open-access papers (continued):
Sharing a sentence is not in itself a finding about the gene and the disease.
AIDS (continued). "The emergence of X4 variants is usually accompanied by a rapid decline in the number of CD4+ T cells and the onset of immunodeficiency and X4 or X4R5 viruses are present in 40-50% of HIV-1-infected individuals who progress to AIDS." (PMID 25430586, 2014). "We aimed to investigate in treated HIV-infected individuals the relationship between the CD4/CD8 ratio and serious non-AIDS events." (PMID 24497929, 2014). "We used population-level longitudinal data from province-wide registries including plasma viral load, CD4 count, drug resistance, HAART use, HIV diagnoses, AIDS incidence, and HIV-related mortality." (PMID 24533061, 2014). "These patients were highly immunocompromised at HAART initiation with a median CD4 of 107 cells/mm3 (IQR 38 to 246) and 62% experienced a prior AIDS event." (PMID 25221931, 2014). "CD4/CD8<0.8 is a surrogate marker of immune-activation/immunosenescence and independently predicts mortality in the HIV-infected patients due to non-AIDS related events." (PMID 25397456, 2014). "Risk factors for poorer survival after ADCs in univariate analysis were, as expected, viro-immunological variables (lower nadir- and CD4+ T-cell count at diagnosis, detectable HIVRNA, previous AIDS event) and IDVU mode of infection." (PMID 24760049, 2014). "From 2007 to 2009, the proportion of CD4 cell count monitoring for people diagnosed with HIV and AIDS increased from 45.3% and 10.1% in 2007 to 54.2% and 62.5% in 2009, respectively." (PMID 24901790, 2014). "The gradual decline of CD4+T-cells in HIV-infected patients is one of the most fundamental and controversial issues in AIDS research." (PMID 24963975, 2014). "Against this background, this study sought to establish the relationship between the CD4 count, viral burden and HRQOL and their differences among treatment-naïve people with AIDS and people with HIV who have been on treatment for 12 months." (PMID 23777555, 2013). "When CD4<200 cells/mm3 was included, 24.0% of HAVACS patients had an AIDS-defining event compared to 6.4% of NHS (p<0.0001)." (PMID 23658717, 2013). "A previous investigation conducted in Yunnan and Guangxi showed that the overall median CD4 cell count of the newly identified HIV and AIDS cases in years 2005 to 2009 was 285 cells/mm3, and 63% of the patients had CD4 counts <350 cells/mm3." (PMID 24024658, 2013). "All HIV-positive patients presented with manifest disease (AIDS), 58.7% of them with an AIDS-defining illness at the time of ICU admission, median CD4 count of 25 cells/mm3 (12.5–100.5 cells/mm3), and median log RNA (HIV-1) of 5.1 (4.6–5.7)." (PMID 23374857, 2013). "In summary, progression to AIDS and death following HIV diagnosis differed in age at diagnosis, transmission categories and CD4+ T-cell counts." (PMID 24376638, 2013). "Adolescents as young as 16 used terminology such as “monitoring a CD4 count,” and knew the difference between the HIV virus and an AIDS diagnosis." (PMID 24023613, 2013). "Precisely, FIV infection results in an overall decrease of CD4+ T cells, an activation of CD4+CD25+ regulatory T cells, a dysregulation of cytokines, and a general immune hyperactivation leading to AIDS." (PMID 23409138, 2013). "Late HIV diagnoses are not exclusive to resource-limited countries: in 2010, 28% of new UK HIV diagnoses had CD4 counts < 200 cells/μL17 and in North America in 2008, 33% of newly HIV-diagnosed patients developed AIDS within one year." (PMID 23046967, 2013). "At the WIHS enrollment, distributions of age, race, AIDS diagnosis, HIV viral load, CD4+ and CD8+ cell counts were significantly different between HAART use and HAART naïve women." (PMID 24373482, 2013). "The objective of this study was to establish the relationship between the CD4 count, viral burden and HRQOL and their difference among treatment-naïve people with AIDS and people with HIV who have been on treatment for 12 months." (PMID 23777555, 2013).
AIDS (continued). "This study compared the level of CD4 count, viral load and health-related quality of life (HRQOL) between treatment-naïve AIDS patients and a cohort of people living with HIV who have been on treatment for 12 months." (PMID 23777555, 2013). "Fitting the non AIDS-related factors (ie excluding HIV viral load and CD4 cell count) into the Cox regression multivariate model, independent predictors of death were found to be male sex, co-morbid tuberculosis and HBV infection." (PMID 25328814, 2013). "This was an immunological and virological sub-study of the Paediatric European Network for Treatment of AIDS (PENTA) 11 trial, which compared CD4-guided PTI of antiretroviral therapy (ART) with continuous therapy (CT) in children." (PMID 24194841, 2013). "CD4+ T-cell depletion is a widely recognized prognostic marker for short and long term outcomes in HIV and AIDS." (PMID 24204912, 2013). "Progression to AIDS and death following HIV diagnosis differed in age at diagnosis, transmission categories, CD4+ T-cell counts and HAART." (PMID 24376638, 2013). "Reduced thymic output most likely contributes to the failure to compensate for increased destruction of CD4+ T cells in lymphoid tissues in HIV-1 infected patients, ultimately resulting in AIDS." (PMID 24237970, 2013). "Epidermal LC isolated from AIDS patients have a range of 107 to 3,645 HIV-1 DNA copies per 105 LC, comparable to that found in CD4+ T cells." (PMID 24278768, 2013). "In that 64 patient’s CD4 counts <200/ul considered as AIDS according to the CDC criteria and 43 patients CD4 counts >200/ul considered as Non- AIDS." (PMID 23795271, 2013). "The results of the univariate analysis indicated significant differences among age at diagnosis, transmission categories, marital statuses, educational level, CD4+ T-cell count within 6 months at diagnosis, concurrent HIV/AIDS diagnosis, and HAART." (PMID 24376638, 2013). "Let us briefly view the mechanisms, which memory CD4 T-cells employ to play the pivotal roles in eradication of HIV and cure of AIDS." (PMID 24151495, 2013). "This study therefore examined the relationship between body weight (body mass index -BMI), immune status (CD4 count), and selenium concentration at diagnosis and evaluated the impacts of HAART on same parameters among HAART-naive HIV/AIDS after 48 weeks." (PMID 24198891, 2013). "Resting CD4+ T-cells are essential for the establishment and maintenance of HIV-1 latency as they can generate viral reservoirs in AIDS patients treated with antiretroviral drugs." (PMID 24523981, 2013). "We specifically address studies and approaches that focus on functional CD4 T-cell helped immune memory, a foundation and the mechanism of patient anti-HIV immunity, vaccination, a cure and a functional cure of AIDS after HAART." (PMID 24151495, 2013). "Concomitant with the decline of CD4 cells in the peripheral blood, the frequency of the CD4+ CD28 null subset increases with disease progression and eventual progression to AIDS." (PMID 24396625, 2013). "Oral administration of NAC can cause an increase in the whole blood GSH levels in HIV infection, reduce viral replication in stimulated CD4 lymphocytes and re-establish immunological reactivity to the HIV virus in AIDS patients." (PMID 23383181, 2013). "Saha and collaborators have shown that CD4+ T cells from 6 LTNPs produce high levels of MIP-1α and MIP-1β in comparison with AIDS subjects, who produce extremely low amounts of these chemokines." (PMID 24167505, 2013). "Multivariate factors significantly associated with mortality included: increasing age among those ≥ 40 years, clinical AIDS event before HAART, CD4+ ≤ 50 cells/mm3, greater HIV RNA level, HCV/chronic HBV, and HIV diagnosis before 1996." (PMID 22339893, 2012). "It is universally accepted that the CD4 counts is a valuable marker of disease progression in HIV and AIDS." (PMID 22583551, 2012).
AIDS (continued). "We observed the same validity of the EQ-5D-5L in discriminating patients at different CD4 groups, and HIV/AIDS stages." (PMID 23116130, 2012). "Implementing our proposed set of test-and-treat interventions to intermediate levels of improvement, including initiation of ART at CD4 counts less than 500 cells/mm3, would meet four of the five National HIV/AIDS Strategy goals by 2015." (PMID 22347994, 2012). "As a result, CD4 count and a few available tests are used in the standard of care for HIV and AIDS mostly due to cost implications." (PMID 23077701, 2012). "We examined the relationship between total social capital and select HIV health status variables including CD4 count, HIV viral load, AIDS diagnosis and HIV medication adherence." (PMID 22414342, 2012). "In the Paediatric AIDS Clinical Trials Group (PACTG) 219 study, 33% of children who initiated treatment with CD4<5% reached normal levels after three years of treatment, compared to 45% after four years in our study." (PMID 23078768, 2012). "Expansion of POC CD4 testing is therefore a priority initiative to improve access to treatment for HIV and AIDS, and several POC CD4 technologies have recently become available, or are expected in the near future." (PMID 22912668, 2012). "Research shows that the surface expression of CCR5 on CD4+ and CD8+ T cells from AIDS patients is higher than subjects infected with HIV but with no symptoms and healthy controls." (PMID 23185351, 2012). "For many years, HAART has been proven to effectively decrease viral load and increase CD4+ T-cell count, thus improving the quality of life of HIV/AIDS patients." (PMID 22971934, 2012). "Mean CD4 count for all non-AIDS patients starting ART was <350 cell/mm3, with baseline CD4 count for patients on Atripla® significantly higher than that for other regimens; baseline CD4 counts for the other three regimens were similar." (PMID 23118869, 2012). "Higher CD8+%, lower CD127+CD4+%, higher CD95+CD8+%, CD38+CD8+%, and CD45R0+CD38+CD8+% characterized LP/AHD/AIDS presentation." (PMID 22110905, 2012). "The objectives of this study are to assess and compare CD4 cell trends, from the time of HIV seroconversion, but prior to antiretroviral treatment initiation, and time to clinical AIDS or death, in persons followed in SSA and European cohorts." (PMID 22412867, 2012). "We determined various factors that influenced the HRQOL of patients with HIV/AIDS, including socioeconomic status (gender, education, employment, and income), HIV/AIDS stages, CD4 cell counts, and the duration of taking ART." (PMID 22911742, 2012). "Less robust CD4 cell recovery on ART has beenassociated with HIV-related disease progression, and with incidence ofnon-AIDS-defining cancers in a cohort study that included some ACTG 384 participants." (PMID 22970105, 2012). "Predictors of poorer HRQOL included being female, lower education level, unemployment, alcohol and drug use, CD4<200 cells/mL, and advanced HIV/AIDS stages." (PMID 23116130, 2012). "While broad Gag- and Vif-specific responses have been correlated to vaccine-induced protection in SIV-challenged macaques, induction of Env-specific CD4+ T-cell responses contributed to enhanced SIV replication and accelerated progression to AIDS." (PMID 23028895, 2012). "The present study was conducted to assess the clinical and microbiological spectrum in HIV/AIDS cases with diarrhea and to correlate the occurrence of such pathogens with stool characters, HIV seropositivity status, and CD4 counts." (PMID 23326669, 2012). "In the literature, applications of the EQ-5D-3L in HIV/AIDS showed its convergent validity with the MOS-HIV, and discriminative validity with AIDS-defining events, disease severity (CD4, viral load, and HIV/AIDS stages)." (PMID 23116130, 2012). "The median baseline CD4 count was 190 cells/μL (interquartile range [IQR] 90 - 310 cells/μL) and 644 (15%) participants had AIDS at baseline." (PMID 21892955, 2011).
AIDS (continued). "CD4+ T cells from HIV-2 infected subjects, who display a longer time of progression to AIDS than HIV-1 infected patients, were more polyfunctional than those found in viral load and CD4+ T cell-matched HIV-1 infected subjects." (PMID 21347287, 2011). "Blood monocytes, CD4 T lymphocytes and resident macrophages are important in vivo cell targets for HIV infection and their role in AIDS pathogenesis are well documented." (PMID 22164280, 2011). "Univariate associations with ALT elevation (p<0.05) included history of AIDS, HBV DNA ≥2,000 IU/ml, HBeAg positive, study visit CD4 <200 cells/ml and nadir CD4 <200 cells/ml." (PMID 22069454, 2011). "Thus, the development of AIDS may occur when the density of CD4+ T cells drops below a limit necessary to provide help (the threshold being around 200 cells/μL of blood for HIV infection), leading to functional defects in CD8+ T cells and antibody-producing B cells." (PMID 21359149, 2011). "AIDS progression (any new WHO Stage 3 or 4 condition), virologic and CD4 cell response, HIV and TB drug resistance, and safety and tolerability of and adherence to HIV and TB drugs will be evaluated, as will the cost-effectiveness of the two strategies." (PMID 21999779, 2011). "Distribution of 395 participants at the CD4 cut-offs of 250cells/mm3 and 350cells/mm3 by WHO HIV/AIDS clinical stages, and sex." (PMID 21589912, 2011). "AIDS diagnosis was based mainly on adapted CDC criteria (88.4% of reports), and 70% of AIDS cases reported had determination of less than 350 CD4 cells/mm3." (PMID 22047047, 2011). "Despite large-scale HIV testing campaigns to hasten diagnosis and the raising of CD4 count thresholds to allow earlier ART eligibility, late presentation for AIDS treatment remains the norm." (PMID 21811403, 2011). "Among other differences, AIDS prior to HAART, baseline VL ≥100,000 copies/ml, and longer time from SC to HAART start were all most common in those with a baseline CD4+ ≤200 cells/mm3." (PMID 21244701, 2011). "While the WHO HIV/AIDS clinical guidelines are an affordable method to determine ART eligibility, routine or low cost CD4 T-cell count, as compared with WHO HIV/AIDS clinical staging in a resource limited setting is very cost-effective for sub Saharan Africa." (PMID 21589912, 2011). "We have estimated the transition probabilities by fitting the model to data on the distribution of the HIV-infected population by CD4 count and the pattern of progression from HIV infection to AIDS death." (PMID 21490782, 2011). "Cohort studies in HIV-positive and AIDS patients indicate that autonomic dysfunction parallels the HIV disease progression-i.e., heart rate variability indices correlate with the CD4 cell count." (PMID 22087127, 2011). "In our multivariable analyses, currently receiving ART for HIV/AIDS was an independent predictor of CIN, even after controlling for current CD4+ T-cell counts and stage of HIV disease." (PMID 20072610, 2010). "The median CD4+ T-cell count was 343/μL (IQR: 244–495) and a large majority (262/303; 86.5%) presented with WHO Clinical Stage I/II of HIV/AIDS." (PMID 20072610, 2010). "CD4+ lymphocyte cell counts were available for 1,466 patients (57.5% of all confirmed HIV/AIDS patients)." (PMID 20226025, 2010). "This laboratory and others have documented Treg mediated immune suppression of both CD4+CD25- and CD8+ lymphocytes during acute and chronic AIDS lentiviral infection." (PMID 21092106, 2010). "Several factors may lead to higher cost-effectiveness ratios in the European setting, including higher rates of risk-factor-based, non-routine HIV testing, higher CD4 counts at diagnosis, and fewer patients presenting to care with AIDS-defining opportunistic diseases." (PMID 20976112, 2010).
AIDS (continued). "The recent decision by the government of Côte d'Ivoire to provide ARV drugs and CD4 tests for free should be considered as a first step, but additional steps must be taken to further alleviate the burden of HIV/AIDS care and treatment in patients on ART." (PMID 20585454, 2010). "Absolute CD4 T cell counts and haemoglobin level are the most important parameters for monitoring progression of HIV to AIDS and also the improvement after initiation of antiretroviral therapy (ARV)." (PMID 19144106, 2009). "There has been a limited number of investigations into the CD4 T-cell response against KSHV: one group reported the identification of two CD4 T-cell epitopes in K12 and K15 in one individual with AIDS-KS." (PMID 19536280, 2009). "Secondary endpoints included: AIDS progression/death; plasma HIV RNA and CD4 responses and safety parameters including IRIS." (PMID 19440326, 2009). "Thus, a more immunogenic BCG may become a useful vector for expressing antigens of other pathogens including HIV and Plasmodium species to produce strong cell-mediated responses, including CD4+ helper responses, as part of vaccination regimens against AIDS, malaria, and other infectious diseases." (PMID 19436730, 2009). "Interviews and investigations performed by public health staff led to an increased yield in the report of CD4 T cell counts and plasma HIV viral loads when compared to HIV/AIDS Surveillance Registry laboratory reports alone." (PMID 19144168, 2009). "Our data are consistent with a potential role of these antibodies in CD4+ T cell depletion in SIV infection and has additional implications for the pathogenesis and treatment of AIDS in humans." (PMID 19360097, 2009). "Our data are consistent with a potential role of these antibodies in CD4+ T cell depletion in SIV infection and has additional implications for the pathogenesis of AIDS in humans." (PMID 19360097, 2009). "Thus, we sought to determine whether GRG status predicted risk of AIDS when the CD4 and viral load may not." (PMID 18776933, 2008). "HAART regimens appear to have positive effects on CD4 count, HIV viral load, and several other measures of physical well-being in patients with advanced AIDS." (PMID 19102765, 2008). "Good performance status, higher CD4 count, whole brain irradiation and HAART have favourable impact on survival in AIDS-related PCNSL." (PMID 18684320, 2008). "In Ethiopia, private labs perform CD4 counts and other HIV/AIDS tests under a quota specified by the Ministry of Health (MOH), and are reimbursed for tests conducted." (PMID 18796148, 2008). "All progressors developed AIDS as defined by persistent CD4+ T-cell depletion below 200 cells/μl, the Centers for Disease Control (CDC)-established surveillance case definition threshold for human AIDS." (PMID 18928523, 2008). "These analyses suggested that in each CD4/viral load stratum, compared to those with a high GRG, twice the number of subjects with a low GRG would need to be treated to prevent one case of AIDS." (PMID 18776933, 2008). "Once the CD4 cell count has decreased to < 200/mm3 or < 14%, HIV infection is known as the acquired immunodeficiency syndrome (AIDS)." (PMID 19936197, 2008). "The cohort consisted of 119 AIDS patients enrolled at the Shattuck Hospital (n = 49) or NNTC (n = 70), and had relatively high plasma VL and low CD4 counts compared to other current cohorts, together with a high frequency of intravenous drug abuse (IVDU)." (PMID 18575590, 2008). "In addition, we did not specifically analyze how the severity of HIV illness might relate to disability, although it is important to note that traditional measures of severity (CD4 count, past AIDS illness) might have less significance with current antiretroviral therapy options." (PMID 18834538, 2008). "RBg-9 also experienced a more rapid depletion of CD4+CD29+ memory T cells in peripheral blood (week 12) than RPn-8, and has progressed to AIDS." (PMID 18928523, 2008).